PLGLA (plasminogen like A (pseudogene))
Description:
May bind non-covalently to lysine binding sites present in the kringle structures of plasminogen. This may interfere with the binding of fibrin or alpha-2-antiplasmin to plasminogen and may result in the localization of activity at sites necessary for extracellular matrix destruction (By similarity).
Synonyms: formerly PLGP2; PLGLA1
Gene: Transcribed unprocessed pseudogene on chromosome 2 (106,382,171 to 106,392,864, forward strand). Ensembl gene ENSG00000240935.
Subcellular location: Secreted
Diseases named in the same sentence as PLGLA in open-access papers:
PLGLA is named in the same sentence as 4 diseases in open-access papers, as found by Europe PMC text mining. Sharing a sentence is not in itself a finding about the gene and the disease. The quoted sentences say what the papers report.
liver cancer (1 paper, 2023). An epithelial or non-epithelial malignant neoplasm that arises from the liver. "Pseudogene PLGLA can inhibit the proliferation and division of liver cancer cells by regulating the miR-324-3p/GLYATL1 axis." (PMID 36941564, 2023).
Stroke (1 paper, 2025). Sudden impairment of blood flow to a part of the brain due to occlusion or rupture of an artery to the brain. "In a proteomics stroke study, researchers identified ICAM-2, STXBP5, PLGLA, C3, and IGHV3-64 as candidate biomarkers in blood, yielding a high (75% to 88%) sensitivity for identifying stroke patients." (PMID 40362186, 2025).
PLGLA also shares sentences with these, for which no sentence is quoted: cancer (1 paper); synovitis (1).